IGSF11 (immunoglobulin superfamily member 11)
Description:
Functions as a cell adhesion molecule through homophilic interaction. Stimulates cell growth.
Synonyms: Bt-IGSF; BTIGSF; CXADRL1; VSIG3; MGC35227; Igsf13; CT119
Tractability: Antibody: UniProt places it where antibodies can reach, with medium confidence; UniProt predicts a signal peptide or a membrane-spanning region; its Gene Ontology location is reachable by antibodies, with medium confidence. PROTAC: its protein half-life has been measured.
Gene: Protein-coding gene on chromosome 3 (118,900,557 to 119,146,068, reverse strand). Ensembl gene ENSG00000144847.
Subcellular location: Cell membrane
Subcellular location (Human Protein Atlas): Cell Junctions; Cytosol; Nucleoplasm
Gene Ontology:
Molecular function: ionotropic glutamate receptor binding; protein binding
Biological process: homophilic cell-cell adhesion; cell-cell adhesion; positive regulation of long-term synaptic potentiation; regulation of presynapse assembly; regulation of synaptic plasticity; trans-synaptic signaling
Cellular component: cell-cell junction; plasma membrane; synapse
Genetic constraint (gnomAD): Loss-of-function variants: 19 observed, 34.27 expected, observed/expected ratio (o/e) 0.55, 90% interval 0.39 to 0.81. The upper end of that interval is the gene's LOEUF score, 0.81, which puts it in group 3 of 6, group 1 being the genes least tolerant of losing a copy. Missense variants: 408 observed, 494.67 expected, observed/expected ratio (o/e) 0.82, 90% interval 0.76 to 0.89. Synonymous variants: 198 observed, 190.03 expected, observed/expected ratio (o/e) 1.04, 90% interval 0.93 to 1.17.
Homologues: Orthologues: chimpanzee IGSF11 (99% identical), macaque IGSF11 (97% identical), dog IGSF11 (94% identical), pig IGSF11 (93% identical), rabbit IGSF11 (93% identical), guinea pig IGSF11 (89% identical), mouse Igsf11 (89% identical), rat Igsf11 (84% identical), zebrafish igsf11 (64% identical), tropical clawed frog IGSF11 (61% identical). Paralogues in human: CXADR (27% identical), ESAM (25% identical), CLMP (23% identical), VSIG1 (22% identical), VSIG2 (21% identical), GPA33 (20% identical), VSIG8 (19% identical), JAM2 (16% identical), F11R (15% identical), JAM3 (15% identical), MXRA8 (14% identical), MUC15 (11% identical), and 2 more.
Diseases named in the same sentence as IGSF11 in open-access papers:
IGSF11 is named in the same sentence as 48 diseases in open-access papers, as found by Europe PMC text mining. Sharing a sentence is not in itself a finding about the gene and the disease. The quoted sentences say what the papers report.
gastric cancer (8 papers, 2012 to 2025). A primary or metastatic malignant neoplasm involving the stomach. "High expression levels of IGSF11 have been correlated with aggressive clinical features in several cancers, including gliomas, hepatocellular carcinoma, melanoma, and gastric cancer." (PMID 40867265, 2025). "Independently, BT-IgSF was also found to be up-regulated in intestinal-type gastric cancers and designated IgSF11 (moreover it was also termed V-set and Immunoglobulin domain containing 3, abbreviated VSIG-3)." (PMID 36607983, 2023). "In gastric cancer, based on IGSF11, the polypeptide vaccine that is designed can effectively enhance the function of CTLs (cytotoxic T lymphocytes), which are identified for their favorable role in tumor inhibition and patients’ survival." (PMID 35831836, 2022). "IGSF11 was also identified independently as a gene up-regulated frequently in intestinal-type gastric cancers." (PMID 22916035, 2012). "While IGSF11 shows minimal expression in normal tissues, recent studies show that it is significantly upregulated in various cancers, such as colorectal cancer, hepatocellular carcinoma, melanoma, gastric cancer, and breast cancer." (PMID 40867265, 2025). "Targeting the extracellular domain of IGSF11 with an antibody may also offer a promising alternative approach for gastric cancer treatment." (PMID 40867265, 2025). "In gastric cancer St-4 cells, the reduced expression of IGSF11 decreases the transfected St-4 cells number, the growth inhibitory effect can also be found in NIH3T3 cells and proved by colony formation assay in gastric cancer, but the intrinsic mechanisms are still unclear." (PMID 35831836, 2022). "Furthermore, elevated VSIG-3/IGSF11 (a ligand of VISTA) expression has been observed in colorectal, hepatocellular, and intestinal gastric cancers." (PMID 40867265, 2025). "Exclusion for immune cells, VISTA expresses higher in tumors and may interact with IGSF11 in immune regulation, including NSCLC, ovarian cancer, gastric cancer, colorectal cancer, soft tissue sarcoma and oral squamous cell carcinoma." (PMID 35831836, 2022). "Watanabe and colleagues recognized IGSF11 as a new therapeutic target for gastric cancer and found two peptide sequences originating from IGSF11 that could provoke cytotoxic T lymphocyte (CTL) responses directed at IGSF11-expressing gastric cancer cells in an HLA-A*0201-restricted manner." (PMID 40867265, 2025).
glioma (7 papers, 2020 to 2025). A benign or malignant brain and spinal cord tumor that arises from glial cells (astrocytes, oligodendrocytes, ependymal cells). "To explore the association between IgSF11 expression and the presence of various immune cell populations within glioma microenvironment, we performed a duple clustering of glioma cases using the median as a cut off for patient’s stratification." (PMID 33604291, 2020). "The expression profile of IgSF11 gene was significantly linked to glioma grades (p < 0.0001), histological type (p = 0.0169), patients age (p < 0.0001), molecular subtype (p = 0.0001) and IDH mutation status (p = 0.0018)." (PMID 33604291, 2020). "Importantly, elevated IGSF11 expression was associated with poorer overall survival, indicating its potential as a prognostic biomarker and a therapeutic target in gliomas." (PMID 40867265, 2025). "Besides, about 16.66% of glioma samples (5 out of 30 cases) showed a positive staining of IgSF11 on tumor-associated inflammatory cells." (PMID 33604291, 2020). "Indeed, increased expression of IgSF11 in advanced human gliomas associated with a poor overall survival." (PMID 33604291, 2020). "Ghouzlani and colleagues have shown that IGSF11 expression was markedly elevated in patients with high-grade gliomas." (PMID 40867265, 2025). "Analysis of an independent cohort from The Cancer Genome Atlas (TCGA) further validated the upregulation of IGSF11 transcripts in high-grade gliomas." (PMID 40867265, 2025). "In this study, we described an interestingly elevated expression profile of IgSF11 in high versus low human glioma patients." (PMID 33604291, 2020). "In order to confirm IgSF11 gene expression results obtained at the transcript level, IgSF11 protein analysis was performed on 30 human glioma samples (13 low grade (I/II) and 17 high grade (III/IV) cases) by immunohistochemistry." (PMID 33604291, 2020). "This is the first report to the best of our knowledge on the role of IgSF11 in human glioma progression." (PMID 33604291, 2020). "In contrast, the immunosuppressive gene TGF-β exhibited high levels of expression in glioma cases with higher levels of IgSF11 gene expression (p < 0.0001)." (PMID 33604291, 2020). "IgSF11 gene expression was significantly upregulated in high grade glioma tissues, compared to low grade." (PMID 33604291, 2020). "This has prompted us to explore the role of IgSF11 in glioma progression using two independent tumor cohorts, local human glioma samples, and TCGA cohort." (PMID 33604291, 2020). "In summary, in this study, which corresponds to the first evaluation of IgSF11 expression and role in human glioma, we presented evidence for gradual expression of IgSF11 in patients presenting with gliomas, depending on distinct grades." (PMID 33604291, 2020). "Surprisingly, strong IgSF11 staining was observed in all cases of glioma (low and high grades), contrasting with mRNA data." (PMID 33604291, 2020). "On the other hand, when we compared IgSF11 expression according to patients’ grades, we revealed a significantly higher expression in high grade glioma tissues relative to low grades (p = 0.0047)." (PMID 33604291, 2020). "Our data strongly suggest that IgSF11 is an immune checkpoint, which is upregulated in advanced human gliomas and contributes to the immunosuppressive state resulting in a poor clinical outcome in glioma patients." (PMID 33604291, 2020). "High grade gliomas (glioblastoma) presented high level of IgSF11 expression compared to low grade (p < 0.0001)." (PMID 33604291, 2020). "Overall, these observations indicated that IgSF11 mRNA was highly expressed in high grade gliomas compared to low grades." (PMID 33604291, 2020). "At the best of our knowledge, this is the first investigation of the role of IgSF11 in clinically resected human glioma tumors." (PMID 33604291, 2020). "Overall, our data indicated that IgSF11 protein was strongly expressed on tumor and inflammatory cells in human gliomas." (PMID 33604291, 2020).
glioma (continued). "IDH wild-type glioma showed a significantly distinct pattern of IgSF11 expression from IDH mutant glioma with significant upregulation in IDH wild-type glioma (p < 0.0001)." (PMID 33604291, 2020). "Notably, glioma patients with high IGSF11 levels exhibit increased immune cell infiltration; however, their microenvironment was predominantly immunosuppressive." (PMID 40867265, 2025). "VSIG-3 (IgSF11) is a member of the immunoglobulin superfamily which is highly expressed in gliomas." (PMID 40895574, 2025). "In addition, IGSF11 protein has been detected in various glioma samples, supporting its relevance at both the transcript and protein levels." (PMID 40867265, 2025). "IgSF11 mRNA expression was assessed in human glioma patients at different grades using 2 independent cohorts, a set of 52 Moroccan samples, including 20 glioma tissues, 22 PBMC samples taken before and 10 PBMC samples taken after surgery; and a series of 667 patients from TCGA." (PMID 33604291, 2020). "Indeed, the potent immunosuppressive cytokine TGF-β, which is known to be involved in the process of glioma progression, showed high levels of expression in patients with high levels of IgSF11." (PMID 33604291, 2020). "This suggests that IgSF11 would use similar mechanisms as other critical immune checkpoints such as the PDL-1/PD-1 axis, whose activity is known to be associated with a bad prognosis for glioma patients." (PMID 33604291, 2020). "High IgSF11 expression in advanced glioma patients correlated with higher infiltration of immune cells, which would be weakly functional, due to the highly immuno-suppressive microenvironment (elevated expression of immune checkpoints and cytokines such as TGFβ)." (PMID 33604291, 2020). "IgSF11 protein also showed a significant expression in low and high-grade gliomas." (PMID 33604291, 2020). "Expression of IgSF11 according to glioma patient characteristics in the TCGA cohort." (PMID 33604291, 2020). "Interestingly, IgSF11 expression level appeared to be higher in all glioma samples (high and low grades) compared to PDL-1 (p < 0.0001)." (PMID 33604291, 2020). "Altogether, our data indicate that IgSF11 could be considered as a promising therapeutic target in advanced gliomas." (PMID 33604291, 2020). "Also, this is the largest and most comprehensive study describing the expression of IgSF11 in human glioma samples using two distinct cohorts." (PMID 33604291, 2020). "Our study identified IgSF11 as a possible promising therapeutic target in advanced human glioma." (PMID 33604291, 2020). "IgSF11 protein was detected in endothelial cells and tumor cells in all grades of gliomas." (PMID 33604291, 2020). "In addition, IgSF11 transcripts were elevated in healthy donors, glioma tissues and PBMCs before surgery compared to PBMCs taken from patients after surgery (p = 0.0233), (p = 0.0055), and (p = 0.0235), respectively." (PMID 33604291, 2020). "IgSF11 showed a significant mRNA expression in samples from glioma patients." (PMID 33604291, 2020). "Interestingly, IgSF11 protein appeared to show a similar expression profile on different glioma grades, suggesting that IgSF11 gene might be subject to post-transcriptional regulation." (PMID 33604291, 2020). "Thus, the main objective of this study was to explore the role of IgSF11 in human gliomas." (PMID 33604291, 2020). "IgSF11 could be considered as a possible promising therapeutic target in advanced human gliomas." (PMID 33604291, 2020). "This study aimed to explore the expression and role of IgSF11, an emerging immune checkpoint and a ligand of VISTA, in human gliomas." (PMID 33604291, 2020). "Even the immune regulation of IGSF11 has just been proved in glioma, but VISTA has been proved to be in many other tumors, thus, the research potential for the mechanisms of IGSF11 in tumor immune regulation is enormous, since the intracellular mechanisms are still unclear." (PMID 35831836, 2022).
glioma (continued). "One of the known ligands of VITSA, the immunoglobulin superfamily 11 gene (IgSF11), is found with elevated expression particularly in high grade glioma (also named HGG) and correlates with worse prognosis, suggesting the potential prognostic value of VISTA and IgSF11." (PMID 35135556, 2022). "However, glioma microenvironment infiltrating CD8 and CD4 cells would exhibit limited effector functions, owing to the higher expression level of the immuno-suppressive molecule, IgSF11, in addition to other immune checkpoints." (PMID 33604291, 2020). "IgG1 isotype was used as a negative control to assess IgSF11 protein expression in glioma tissues." (PMID 33604291, 2020).
hepatocellular carcinoma (7 papers, 2020 to 2025). A malignant tumor that arises from hepatocytes. "Watanabe and colleagues further reported that IGSF11 expression is upregulated in colorectal cancer, hepatocellular carcinoma, and intestinal-type gastric cancer." (PMID 40867265, 2025). "IgSF11 expression has been evaluated on other cancer types, such as gastrointestinal and hepatocellular carcinoma." (PMID 33604291, 2020).
breast carcinoma (5 papers, 2009 to 2025). "Their observations suggest that increased aggressiveness in breast cancer cells is linked to higher levels of proteins within the VISTA/IGSF11/PSGL-1 axis." (PMID 40867265, 2025). "Recent studies have revealed overexpression of IGSF11 in several malignancies, including colorectal, gastric, hepatocellular, and breast cancers." (PMID 40867265, 2025). "In breast cancer models, IGSF11 expression appears to be influenced by TGF-β signaling." (PMID 40867265, 2025). "In the breast tumor model, the expression of IGSF11 is associated with TGF-β; TGF-β regulates the EMT triggers, which promote the expression of LincRNA Platr18, then induces the expression of IGSF11, and the whole process may be related to the metastasis of breast cancer." (PMID 35831836, 2022).
glioblastoma (3 papers, 2020 to 2025). The most malignant astrocytic tumor (WHO grade IV). "In the case of IGSF11, the UALCAN data revealed significantly elevated expression in multiple cancer types, including glioblastoma multiforme (GBM), skin cutaneous melanoma (SKCM) and lung squamous carcinoma (LUSC) compared with their respective normal tissue counterparts." (PMID 40867265, 2025).
male infertility (2 papers, 2019 to 2021). The inability of the male to effect fertilization of an ovum after a specified period of unprotected intercourse. "Our results show that deficiency for adhesion molecule IGSF11, which is expressed in both Sertoli cells and germ cells, leads to male infertility in mice." (PMID 34491997, 2021). "Disruption of Igsf11 or conditional knockout of Igsf11 in Sertoli cells results in male infertility in mouse." (PMID 34491997, 2021). "The IGSF11 gene was identified in Sertoli cells in mice and its under-expression resulted in male infertility, atrophic testicles, azoospermia, and spermatogenesis arrest." (PMID 30677076, 2019).
oral squamous cell carcinoma (2 papers, 2022 to 2024). "Considering the differences of IGSF11 and VISTA studies in different tumors, we consider that the role of IGSF11 in non-small-cell lung cancer, ovarian cancer and oral squamous cell carcinoma, even in esophageal carcinoma, worth further exploration." (PMID 35831836, 2022).
astrocytoma (1 paper, 2020). "In addition, astrocytoma showed an elevated expression of IgSF11 in comparison to oligoastrocytoma (p = 0.0237) and oligodendroglioma (p = 0.0387)." (PMID 33604291, 2020).
brain malformations (1 paper, 2016). "IGSF11 is an immunoglobulin (Ig) superfamily member, preferentially expressed in the brain and testis; however, an involvement in the etiology of brain malformations has not been reported and a similar duplication has not been observed yet." (PMID 27087860, 2016).
colon cancer (1 paper, 2025). "Additionally, combining SG7 with anti-PD-1 therapy in the MC38 colon cancer model produced similar positive results, highlighting the therapeutic potential of targeting the IGSF11–VISTA pathway." (PMID 40867265, 2025).
hyperparathyroidism (1 paper, 2024). Hyperfunction of the parathyroid glands resulting in the overproduction of parathyroid hormone. "Genetically predicted expression of IGSF11, PIK3C3, and SLC40A1 retained significant associations with hyperparathyroidism risk in GTEx thyroid tissue cohort (P < 1.25e−02, inverse-variance weighted methods)." (PMID 38499600, 2024). "Five drug targets (CMKLR1, FSTL1, IGSF11, PIK3C3 and SLC40A1) showed significant causation with hyperparathyroidism in both eQTLGen and GTEx cohorts by MR analysis." (PMID 38499600, 2024).
lipoma (1 paper, 2021). A benign, usually painless, well-circumscribed lipomatous tumor composed of adipose tissue. "Among the candidate selection signal genes, the LIM domain containing the preferred translocation partner in lipoma (LPP), immunoglobulin superfamily member 11 (IGSF11), and lamin B2 (LMNB2) genes has been associated with immune responses and disease sensitivity." (PMID 34072132, 2021).
lung adenocarcinoma (1 paper, 2023). A carcinoma that arises from the lung and is characterized by the presence of malignant glandular epithelial cells. "Among them, low expression of C12orf56, DLX5, DSC3, FEZF1, GSTA1, H2BC9, IGSF11 and high expression of EREG, CEACAM6, SLC34A2 in lung adenocarcinoma were found to predict poor prognosis for patients." (PMID 37035196, 2023).
lung carcinoma (1 paper, 2023). "Finally, our work shows that the adenosine methylation of miR-125a-5p is analyzable from EVs/exosomes from longitudinal blood samples and that such EVs/exosomes modulate the IGSF11/VSIG3 expression in lung cancer cells to promote an immune escape phenomenon." (PMID 37370798, 2023).
melanoma (1 paper, 2025). A malignant, usually aggressive tumor composed of atypical, neoplastic melanocytes. "Consequently, targeting IGSF11 boosts T-cell-mediated anti-tumor immune responses and also suppresses the proliferation of A2058 melanoma cells, highlighting its dual therapeutic potential in melanoma treatment." (PMID 40867265, 2025).
Neurodevelopmental delay (1 paper, 2024). "In addition, in utero exposure to HG is associated with smaller brains and neurodevelopmental delay at age 10,58 so the link to head circumference at birth and IGSF11 and PGR loci for HG require further investigation." (PMID 39764105, 2024).